PI16 (peptidase inhibitor 16)
Diseases named in the same sentence as PI16 in open-access papers (continued):
Sharing a sentence is not in itself a finding about the gene and the disease.
tumor (20 papers, 2012 to 2025). "Notably, high expression of PI16 exists in fibroblasts of metastatic lymph nodes compared with tumor-associated fibroblasts." (PMID 37914722, 2023). "Using differential gene expression analysis between classical Fb subtypes and CAFs, we identified CAF-enriched transcripts, including Postn, Cilp, Loxl1, Thy1, and Pi16, previously associated with CAF identity in various tumor types." (PMID 41223283, 2025). "This showed that universal (PI16+) fibroblasts from tumours show evidence of activation and inflammatory changes (including expression of FAP, COL1A1, IGF1)." (PMID 39757146, 2025). "Specifically, in cluster 1, we found that the chemokine CCL19 produced by fibroblasts and markers of tumor-associated fibroblasts such as SFRP1, PI16, and ADH1B were significantly expressed." (PMID 40538442, 2025). "In our initial HNSCC analysis, ~ 50% of the (universal) PI16 + fibroblast cluster from tumour samples were labelled as IGF1 + CAF in the larger PCFA dataset." (PMID 39757146, 2025). "IVIS imaging showed PI16 overexpression inhibited tumour growth, while PI16 knockdown promoted tumour growth." (PMID 37525118, 2023). "PI16-knockdown tumours showed spine-like structures penetrating muscle, indicating high invasiveness." (PMID 37525118, 2023). "In our study, we discovered that PI16 plays a vital role in suppressing the development of tumours and the progression of metastasis in BLCA by inhibiting the activity of NF-κB through ANXA1-dependent ubiquitination of NEMO." (PMID 37525118, 2023). "We also found that PI16 was upregulated in fibroblasts of metastatic lymph nodes compared to tumor tissues (P < 0.001)." (PMID 37914722, 2023). "ESCC patients with high PI16 expression in tumor interstitial tissues exhibited worse survival than patients with low PI16 expression (P = 0.0028, log-rank)." (PMID 37914722, 2023). "Multivariate analysis indicated that high PI16 expression in tumor interstitial tissues was an independent prognostic factor for ESCC patients undergoing platinum-based chemotherapy." (PMID 37914722, 2023). "For example, C03_PI16 expressed several marker genes, such as COL14A1, CFD, GSN and PI16, similar to the major fibroblast subpopulations in normal tissue and early‐stage tumour in a previous study." (PMID 38115703, 2023). "We also examined PI16 expression in interstitial tissues in ESCC tumor samples of patients receiving platinum-based therapy postsurgery and found that high PI16 expression in tumor interstitial tissues was an independent prognostic factor for ESCC patients." (PMID 37914722, 2023). "The tumour‐enriched cluster F01 highly expresses PI16 which enhances the transendothelial migration of monocytes." (PMID 35608199, 2022). "PI16 has been linked to fibroblast activation and ECM organization, whereas SMCs are known to generate contractile forces that enhance stromal stiffness and interstitial pressure, both of which promote tumor cell invasion and metastasis." (PMID 41246350, 2025). "This approach highlighted several putative iCAF-enriched populations from both normal and tumour samples; in normal tissues these included Stress-response Fib, CXCL8 + Breast Fib and universal (PI16+) fibroblasts; in tumours, IL11 + CAF, IGF1 + CAF and proto-CAF." (PMID 39757146, 2025). "Based on previously reported phenotypic features of fibroblasts 40, we identified 8 distinct subpopulations: matrix CAFs (mCAFs), inflammatory CAFs (iCAFs), interferon response CAFs (ifnCAFs), reticular-like CAFs (rCAFs), tumor-like CAFs (tCAFs), PI16+ CAFs, SMCs, and Pericytes." (PMID 40303346, 2025). "In tumour tissue, on day 0, Pi16+ cells and Lrrc15+ cells were detected." (PMID 36171287, 2022). "Desmoplastic and WNT5A+ inflammatory fibroblasts were indicated as the sources of tumor-enriched ECM proteins, while ADAMDEC1+ expressing fibroblasts and PI16+ expressing fibroblast were identified as the sources of NAT-enriched ECM proteins." (PMID 40032993, 2025).
tumor (continued). "Single cell analysis identified six major fibroblast subgroups; universal (PI16+) fibroblasts, ADH1B + fibroblasts and CCL19 + FRC-like fibroblasts were present in normal tissue and tumours." (PMID 39757146, 2025). "Focusing on CAFs, our analysis revealed a novel subpopulation marked by CD34+PI16+, which gave rise to the classical ACTA2+MCAM+ CAFs in tumor, also known as myCAF (data unpublished)." (PMID 39401181, 2024). "In 161 ESCC tumor tissues from the TCGA ESCA database, the tissues were distributed according to quartiles of PI16 mRNA levels." (PMID 37914722, 2023). "LN-Fbs secreted increased levels of high-molecular-weight PI16 (peptidase inhibitor 16) and promoted cisplatin resistance in ESCC tumor cells." (PMID 37914722, 2023). "IHC of subcutaneous tumours showed NF-κB/p65 nuclear expression and MMP9 (a marker of invasion and NF-κB target) decreased in the PI16 overexpression group but increased in the PI16 knockdown group." (PMID 37525118, 2023). "We further tested the correlation between α-SMA and PI16 expression in fibroblasts of these ESCC tumor tissues and metastatic lymph nodes and observed a positive correlation between α-SMA and PI16 expression (R = 0.42, P < 0.001, Spearman’s)." (PMID 37914722, 2023). "Some targets (PI16, WNT2) not only showed differential expression in T1CAFs, but also in CAFs from later tumor stages." (PMID 37085135, 2023). "Among the nine cell states associated with fibroblasts, five (ADAMDEC1+ fibroblast, BMP4+ fibroblast, intestinal smooth muscle, myofibroblast, PI16+ fibroblast) were identified as NAT-enriched, and three (WNT5A+ fibroblast, pericyte, desmoplastic fibroblast) were identified as tumor-enriched." (PMID 40032993, 2025). "For example, ADAMDEC1+ fibroblasts, PI16+ fibroblasts, and IgA plasma appear to be enriched in NAT tissues, in contrast to desmoplastic fibroblasts, macrophages, Treg cells, and IgG plasma, which exhibit a higher proportion in tumor tissues." (PMID 40032993, 2025). "In addition to the tumor cells (dsRED+), we also found another cell cluster lacking the expression of dsRED that similarly express mesenchymal genes, but which was enriched for additional genes previously associated with CAFs, such as Rarres2, Pi16, Fap, Lum, Sfrp2, Dpt, and Col14a1 5,35." (PMID 38509063, 2024). "Currently, we identified that the downregulation of PI16 was positively correlated with unfavourable survival and prognosis of patients with BLCA and could serve as a tumour suppressor in BLCA progression." (PMID 37525118, 2023). "Furthermore, through RNA-seq and secretome assessment by mass spectrometry, we identified the LN-Fb-secreted molecule, namely, PI16 (100/108 kDa, high molecular weight), which is potentially responsible for providing chemoresistance to cisplatin in ESCC tumor cells in metastatic lymph nodes." (PMID 37914722, 2023). "In naive, non-tumour-bearing skin, Lrrc15 expression was absent and all cells were uniformly Pi16+." (PMID 36171287, 2022).
cancer (8 papers, 2020 to 2025). A tumor composed of atypical neoplastic, often pleomorphic cells that invade other tissues. "Indeed, WNT2 up-regulation and loss of PI16 expression already have been reported in CAFs from advanced cancers." (PMID 37085135, 2023). "To explore the potential role of PI16 in carcinogenesis, we analysed data from the TNMplot database and found PI16 expression was downregulated in 22 human cancers." (PMID 37525118, 2023). "PI16, almost an unknown protein in cancer research, needs further deeper investigations." (PMID 32779397, 2020).
infection (2 papers, 2023 to 2025). The state of being infected such as from the introduction of a foreign agent such as serum, vaccine, antigenic substance or organism. "When examining the tissue responses to infection at the single-cell level, we identified that Dpp4+Pi16+ interstitial preadipocytes upregulate Il17ra in response to T. brucei infection, indicating that the capacity of these cells to sense IL-17 signalling is augmented during infection." (PMID 37923768, 2023).
adenocarcinoma (1 paper, 2020). A common cancer characterized by the presence of malignant glandular cells. "In this study, we identified the differential gene, PI16, using TCGA datasets of five different adenocarcinomas." (PMID 32779397, 2020). "In this study, we performed comprehensive analysis of TCGA datasets of five different adenocarcinomas and identified PI16 as one of the top differential genes." (PMID 32779397, 2020).
PI16 also shares sentences with these, for which no sentence is quoted: arteriosclerosis (1 paper); cardiovascular diseases (1); colorectal adenocarcinoma (1); coronary heart disease (1); COVID-19 (1); enteritis (1); Erythema (1); heart diseases (1); hypertrophy (1); immune disorders (1); myocardial infarction (1); Obesity (1); pancreatic cancer (1); pancreatic ductal adenocarcinoma (1); rheumatic carditis (1); Sepsis (1); ulcerative colitis (1).